COMT (catechol-O-methyltransferase)
Diseases named in the same sentence as COMT in open-access papers (continued):
Sharing a sentence is not in itself a finding about the gene and the disease.
schizophrenia (continued). "Hypomethylation of membrane-bound COMT, a schizophrenia and bipolar disorder risk factor, may explain increased COMT expression in PCB-exposed rats." (PMID 40244238, 2025). "Although pharmacogenetic markers related to schizophrenia and clinical outcomes of antipsychotic treatment are areas of intense study, relatively few data are available on risperidone monotherapy in relation to both COMT and NRG1 polymorphisms." (PMID 39062492, 2024). "Furthermore, COMT polymorphisms have also been associated with neuropsychiatric treatment response and symptoms, given the significance of rs4680 in schizophrenia and bipolar disorder." (PMID 39338193, 2024). "Among many COMT polymorphisms, rs4680 and rs4818 were frequently associated with schizophrenia." (PMID 39062492, 2024). "Another study has focused on COMT polymorphism and abstraction in patients with schizophrenia." (PMID 37510262, 2023). "Concerning haplotype associations, male patients with schizophrenia who were COMT rs4818–rs4680 GA haplotype carriers had the highest scores on G1 item (somatic concern), whereas GG haplotype carriers had the lowest scores on G2 (anxiety) and G6 (depression) items." (PMID 37510262, 2023). "This leads to persistently unstable and inefficient activity of the prefrontal cortex network, which may be a mechanism underlying the involvement of COMT in schizophrenia." (PMID 37575581, 2023). "Nevertheless, we hypothesize that different COMT variants may contribute to our understanding on the complexity of psychopathology in schizophrenia and our results may provide a small contribution to the field." (PMID 37510262, 2023). "Future studies exploring the associations of COMT polymorphisms and depressive symptoms in schizophrenia need to consider childhood and life-time stressors, which may strongly influence this relationship." (PMID 37510262, 2023). "Given the important role of abstract thinking in schizophrenia, it remains to be determined whether males with low-activity COMT alleles, who had worse N5 scores, differ in the degree of improvement of deficits in abstract thinking." (PMID 37510262, 2023). "This study provides evidence that the COMT genotype modifies the risk for schizophrenia conferred by T. gondii infection, with it being higher in those individuals with the Met/Met phenotype, intermediate in heterozygous, and lower in those with the Val/Val phenotype." (PMID 35741850, 2022). "These pieces of evidence suggest that the association between COMT Val158Met (rs4680) polymorphism and schizophrenia may be race specific." (PMID 36203835, 2022). "However, the COMT Val158Met (rs4680) polymorphism is found to play an important role in susceptibility to schizophrenia in Caucasian and African Americans." (PMID 36203835, 2022). "Based on the prior clinical, cognitive, and neuroimaging studies, we hypothesize that the COMT Val158Met (rs4680) variant is a potential genetic mechanism underlying the features of sex differences in schizophrenia." (PMID 36203835, 2022). "In particular, we wanted to assess whether the risk for schizophrenia conferred by T. gondii infection is modified by the COMT Val105/158Met genetic variation." (PMID 35741850, 2022). "Moreover, some previous studies also provided evidence suggesting an association between the DS subtype of schizophrenia and gene polymorphisms, including dopamine D2 receptor and catechol-O-methyltransferase (COMT) genes." (PMID 36341400, 2022). "The authors speculated that characteristic pathological features of schizophrenia and the effects of COMT 158Met polymorphism on dopaminergic neuronal function may contribute to the abnormal low-frequency resting EEGs." (PMID 35529780, 2022). "In young adults, the risk of depression could be increased by cannabis use, and some individuals are exposed to a higher risk of schizophrenia with potential involvement of the catechol-O-methyltransferase (COMT) gene polymorphisms." (PMID 35348052, 2022).
schizophrenia (continued). "During the last decades, catechol-O-methyltransferase (COMT) has been implicated in several human diseases, including different neurodegenerative disorders such as schizophrenia and Parkinson’s Disease (PD), estrogen-induced cancers, or cardiovascular diseases." (PMID 35806268, 2022). "Study results of 302 Caucasian male and female schizophrenia patients aged 18–62 suggests that some catechol-O-methyltransferase (COMT) and monoamine oxidase B (MAO-B) genetic variants are associated with a sex-specific increase in the severity of negative symptoms." (PMID 34575706, 2021). "In female patients with schizophrenia, the presence of the G allele or GG genotype of COMT rs4680 and rs4818, as well as GG haplotype rs4818-rs4680, which were all related to higher COMT activity, was associated with an increase in several dimensions of negative symptoms and anhedonia." (PMID 34287249, 2021). "In addition, she had a homozygous valine COMT polymorphism, a genetic variant thought to be associated with a predisposition for schizophrenia in cannabis users." (PMID 34285849, 2021). "However, the potential risk of schizophrenia is thought to be related to a decreased methylation of the COMT gene." (PMID 34831111, 2021). "The Val158Met polymorphism of the gene that leads to a decreased COMT activity in Met158 allele bearers (especially A/A homozygotes) was reported to be linked with neuropsychiatric conditions, such as alcohol dependence, bipolar disorder, schizophrenia." (PMID 33868590, 2021). "This longitudinal study detected a significant association of COMT rs4680 genotype and COMT rs4680–rs4818 haplotype with the much-improved therapeutic response to 8-weeks monotherapy with olanzapine in Caucasian patients with schizophrenia." (PMID 32572118, 2020). "The study assessed the association of the COMT rs4680 and rs4818 polymorphisms with therapeutic response to olanzapine, risperidone, clozapine or other antipsychotic medication after 8 weeks of monotherapy in patients with schizophrenia." (PMID 32572118, 2020). "In addition, variants in CACNA1C, NOTCH4 and COMT had been reported to be associated with schizophrenia in GWAS studies." (PMID 32273551, 2020). "Interestingly, in patients with schizophrenia, homozygosity for COMT Val/Val is associated with significantly greater reduction of auditory hallucinations following tDCS to DLPFC compared to Val/Met and Met/Met carriers." (PMID 32742620, 2019). "Dysregulation of dopamine has long been considered a crucial part of the pathophysiology of schizophrenia and a great deal of research has been done to investigate the link between COMT polymorphisms and schizophrenia, particularly with respect to negative symptoms and cognition." (PMID 31661851, 2019). "In addition, our results are in line with other studies demonstrating sex-specific associations of COMT variants in patients with schizophrenia." (PMID 30018555, 2018). "Variants of the COMT gene have been extensively studied as risk factors for schizophrenia." (PMID 30018555, 2018). "In this study, we aimed to update the pooled effect size estimation by combining the results of studies with appropriate meta‐analytical methods that examine the association between COMT gene rs165599 single‐nucleotide polymorphism and schizophrenia just for case‐control studies." (PMID 30165727, 2018). "In contrast, as far as we are aware, this is the first study to show that in female patients with schizophrenia, the presence of high-activity (G variants) of the COMT rs4680 and rs4818 polymorphisms, and the presence of the G-G/G-G haplotype, is associated with the lower risk of TRS." (PMID 30018555, 2018). "Therefore, studies investigating the association between schizophrenia and COMT gene are increasing day by day." (PMID 30165727, 2018). "Many studies have examined the association between polymorphisms in COMT gene and schizophrenia." (PMID 30165727, 2018).
schizophrenia (continued). "However, genome-wide association studies (GWAS) have confirmed relatively few of these associations though a post-GWAS has identified not only COMT but also GAD1 among a selection of schizophrenia risk genes." (PMID 29429137, 2018). "Therefore, our findings reporting sex-specific associations of COMT variants with the development of treatment-resistance in schizophrenia also contribute to the knowledge in this field." (PMID 30018555, 2018). "Regarding antipsychotic response, the findings of the studies investigating the role of COMT Val158/108Met polymorphism were also conflicting, showing that schizophrenia patients with Met/Met genotype have poor, as well as good response to antipsychotic treatment." (PMID 28358316, 2017). "In schizophrenia and bipolar disorder, presence of the COMT Met allele may further accentuate proline toxicity." (PMID 27622935, 2016). "Furthermore, the polymorphisms of COMT gene are associated with sporadic schizophrenia and mood disorder, respectively." (PMID 27917343, 2016). "Furthermore, the COMT polymorphism has been assumed to be associated with various psychiatric diseases, in particular schizophrenia." (PMID 28101524, 2016). "Whether the pursuit deficit in schizophrenia patients is modulated by the COMT polymorphism is still to be clarified." (PMID 28101524, 2016). "COMT distributions of the schizophrenia patients deviated from Hardy–Weinberg equilibrium (χ2=8.08, df=1, P<0.05), which has been previously reported for this polymorphism in schizophrenia." (PMID 27622935, 2016). "COMT has also been associated with violent behavior in schizophrenia patients." (PMID 25762938, 2015). "If this is so, then the causal explanation that COMT inhibition in schizophrenia may occur via SAMe unavailability for COMT facilitation is less likely and an alternative explanation is required." (PMID 25729574, 2015). "The role of COMT in schizophrenia has been extensively studied, yet results have unequivocally shown that neither genetic variants nor the catalytic activity of the enzyme have great intrinsic influence on schizophrenia risk." (PMID 24639636, 2014). "Notably, the DRD1 gene has been recently found to establish an epistatic interaction with the COMT gene, which predicts schizophrenia risk in males, presumably due to the functional association of D1 receptors and COMT in the PFC." (PMID 24639636, 2014). "This hypothesis is supported by the following example; COMT has been consistently associated with prefrontal regulation of dopamine, which indicates a risk of schizophrenia due to the reduced signal in the prefrontal cortex." (PMID 25060307, 2014). "We investigated whether the COMT Val158Met genotype was associated with cognitive function in 149 healthy controls and 118 patients with schizophrenia." (PMID 24282499, 2013). "Variants in the COMT gene may be associated with susceptibility to schizophrenia, which involves an altered dopaminergic activity in the mPFC." (PMID 23829597, 2013). "The T allele has been shown to reduce dorsolateral prefrontal cortex fMRI activation during working memory performance in schizophrenia, both on its own, and via epistatic interactions with the low-DA COMT 158Val allele, supporting a role of MTHFR in prefrontal DA signaling." (PMID 23882201, 2013). "The dopaminergic pathway is implicated in the neurobiology of cognitive function, and there are genetic associations with functional COMT genotypes related to performance on the neuropsychological tests in bipolar disorder, schizophrenia, ADHD, and in the general population." (PMID 23861766, 2013). "One possibility for this outcome could be that another modifying gene is necessary so that the COMT polymorphism can manifest itself at the level of clinical expression in schizophrenia." (PMID 23184041, 2013). "However, further studies are required to gain more insight into the association of COMT polymorphism with either schizophrenia or its symptomatology." (PMID 23184041, 2013).
schizophrenia (continued). "However, the association between COMT and schizophrenia remains controversial, given that to date family-based association studies and case–control studies include positive and negative findings." (PMID 23184041, 2013). "However, some studies have shown positive association or gender specific association between COMT and schizophrenia." (PMID 23184041, 2013). "Moreover, evidence for COMT associations with behavioral features of schizophrenia has been reported." (PMID 23184041, 2013). "The current study shows an association of COMT gene and schizophrenia in a Greek population." (PMID 23762769, 2012). "Bassett and colleagues examined the role of COMT gene functional Val158Met (rs4680) allele in schizophrenia-related expression in 22q11 deletion syndrome (22q11DS); they found that the Met allele hemizygosity showed significantly worse performance in theory of mind task than Val allele group." (PMID 23209597, 2012). "Indeed DISC1, neuregulin, ERBB4, FEZ1 or COMT knockout mice display many of the pathological and behavioural symptoms associated with schizophrenia." (PMID 22567321, 2011). "Two COMT SNPs (rs165774 and rs4680) which we had previously found to be associated with schizophrenia were genotyped in 250 controls, 147 nicotine-dependent subjects, 120 opiate-dependent subjects and 231 alcohol-dependent subjects to investigate their association with substance dependence." (PMID 22208661, 2011). "The study indicated that the interacting effects within the COMT gene polymorphisms may influence the disease status and response to risperidone in schizophrenia patients." (PMID 21836667, 2010). "Additionally, a haplotype consisting of two noncoding SNPs, rs737865 in intron 1 and rs165599 in the 3′ untranslated region was associated with Schizophrenia and reduced expression of COMT mRNA." (PMID 19365560, 2009). "A functional polymorphism (Val158Met) in the catechol-O-methyltransferase (COMT) gene is implicated in the pathophysiology of schizophrenia by its effect on prefrontal dopamine transmission, and its unique impact on prefrontal cognitive and behavioral phenotypes." (PMID 17173666, 2006). "It has been recently suggested that epigenetic factors may a key role in the development of schizophrenia, and these processes may explain the inconsistent association-study results often observed for variants in the COMT gene." (PMID 16483362, 2006). "Because of the absence of any noticeable decrease in the schizophrenia diagnostic group, it is probable that this decrease in COMT is only present in a subsection of the schizophrenia patients, and presents only a small but detectable increase in risk of developing the disorder." (PMID 16483362, 2006). "For example, the val158met polymorphism in the COMT gene, which is associated with prefrontal dysfunction in schizophrenia, could be assessed for a possible role in psychosis in patients with epilepsy." (PMID 16859554, 2006). "In addition to schizophrenia and bipolar disorder, evidence for a contribution of COMT variants exists for panic disorder, attention deficit hyperactivity disorder, obsessive compulsive disorder, phobic anxiety and anorexia nervosa." (PMID 16232322, 2005). "A study of COMT polymorphisms in modulating working memory in individuals with schizophrenia found that The COMT SNP rs165599, in combination with rs4680, showed a significant association with schizophrenia susceptibility, with the G-A haplotype being a risk factor." (PMID 38689006, 2024). "Overall, our results show the differential impact of functional variants of the DTBPN1 gene interacting with COMT on cognitive functions across sexes in mice and humans, underlying the importance of considering sex as a target for patient stratification and precision medicine in schizophrenia." (PMID 38532008, 2024).
schizophrenia (continued). "Moreover, gene-associated studies showed a possible relationship between the risk of schizophrenia and some variants in genes related to dopamine signaling, i.e., catechol-O-methyltransferase (COMT), monoamine oxidase (MAO), dopamine transporter (SLC6A3), and dystrobrevin-binding protein 1 (DTNBP1)." (PMID 37899392, 2023). "The unique association of lesser severity of PANSS N5 component with the high-activity COMT rs4680 and rs4818 alleles in our study, indirectly suggests the involvement of lower prefrontal dopamine levels in better performance in abstract reasoning in males with schizophrenia." (PMID 37510262, 2023). "Provided that COMT functionality is chiefly influential to dopamine’s metabolism too, we set to test the plausible hypothesis that both T. gondii infection and the COMT genotype exert their risk for schizophrenia by interacting with each other via the modification of dopamine metabolism." (PMID 35741850, 2022). "Hence, COMT polymorphism could predispose patients to a worse schizophrenia baseline situation but to better prognosis if treated with quetiapine." (PMID 34683865, 2021). "COMT mutations have been argued to result in increased dopamine degradation in the frontal lobes, which could provide a molecular basis for some of the symptomatology associated with both schizophrenia and 22q11.2DS106,107." (PMID 32139692, 2020). "COMT encodes catechol-O-methyltransferase, an enzyme that degrades catecholamines such as dopamine, epinephrine and norepinephrine, was the candidate gene in studies investigating DNAm-MRI in the context of working memory in schizophrenia and in healthy participants." (PMID 32151655, 2020). "COMT is among the so-called “hypothesis-driven” candidate genes for the risk of schizophrenia." (PMID 29429137, 2018). "However, the direction of induced changes in neuroplasticity in patients with schizophrenia may also be influenced by external and internal factors such as nicotine smoking and catechol-O-methyltransferase COMT val158 Met polymorphism." (PMID 26993785, 2016). "Although these data should still be regarded as preliminary, several studies suggest that male patients with high-activity COMT may have greater severity of endophenotypes associated with prefrontal deficits in schizophrenia, such as eye movement disturbances prefrontal noise and schizotypal traits." (PMID 24639636, 2014). "Therefore, to explore the possibility that COMT Val108/158Met polymorphism may have susceptibility for schizophrenia, we conducted a case–control study in a Mexican population." (PMID 23184041, 2013). "Therefore, the val variants of the COMT gene may have a different effect on cognitive function in healthy individuals than they do in patients with schizophrenia." (PMID 24282499, 2013). "Notably, COMT is predominantly expressed in the prefrontal cortex, a region associated with executive functioning, working memory, and attentional deficits in schizophrenia." (PMID 24133460, 2013). "In addition, a recent meta-analysis was performed that was based on over 1000 association studies on schizophrenia, and this study highlighted 16 genes, which were mostly dopamine-related, including catechol-O-methyltransferase (COMT) and dopamine receptors D1, D2, and D4 (DRD1, DRD2 and DRD4)." (PMID 24086483, 2013). "Similarly, the COMT polymorphism may have a differential influence in clinical symptomatology depending on the underlying genetic factors responsible for schizophrenia in each individual." (PMID 23184041, 2013). "We propose that in individuals with an underlying susceptibility to schizophrenia, such as a genetic variation of the COMT gene, these androgen-driven increases in dopamine metabolic enzyme mRNAs may contribute to dopamine dysregulation in the substantia nigra at adolescence." (PMID 22867132, 2012). "However the recent finding of a gene-environment effect between COMT val158met and cannabis use in schizophrenia may help to clarify these association findings." (PMID 16483362, 2006).